FADD (Fas associated via death domain)
Diseases named in the same sentence as FADD in open-access papers (continued):
Sharing a sentence is not in itself a finding about the gene and the disease.
cancer (continued). "For example, FADD expression levels may be decreased in certain types of cancer, which may lead to resistance of tumor cells to apoptotic signaling." (PMID 37671047, 2023). "For example, certain types of cancer may resist apoptosis mediated by cytotoxic T cells or natural killer cells by reducing FADD activity." (PMID 37671047, 2023). "FADD may influence the immune system’s response to cancer by regulating T-cell activity and viability." (PMID 37671047, 2023). "Dysregulated FADD expression may contribute to the survival and migration of cancer cells during metastasis." (PMID 37888480, 2023). "Further, AIWrap identified six new genes (VCX3A, CALHM5, ZMYND10, FOXE1, PLAT, FADD) which could be related to smoking in cancer patients, thus providing an opportunity for identifying previously unknown biological functions." (PMID 37853338, 2023). "In recent years, studies targeting FADD have provided many important insights into its function and regulatory mechanisms, as well as the possibility of designing potential therapeutic strategies for cancer and other diseases." (PMID 37671047, 2023). "In addition, due to its crucial roles and differential expression patterns, FADD has exhibited great potential as a valuable therapeutic target and biomarker for cancer diagnosis and treatment prognosis." (PMID 36348274, 2022). "It has been reported that FADD is a crucial regulator of drug resistance during cancer progression." (PMID 36348274, 2022). "In addition, FADD expression was modulated by a series of miRNAs, such as miR-675, miR-7a, and miR-128a, in several types of cancer." (PMID 36348274, 2022). "The crosstalk of FADD with cancer-related signaling pathways, such as mitogen-activated protein kinase (MAPK) and nuclear factor-κB (NF-κB) signaling pathways, is considered a main mechanism through which FADD participates in the modulation of cancer progression." (PMID 36348274, 2022). "FADD has been shown to play an important role in cancer and inflammation." (PMID 36139524, 2022). "The information reviewed herein may expand researchers’ understanding of FADD and contribute to the development of FADD-based therapeutic strategies for cancer patients." (PMID 36348274, 2022). "Changes in the expression of FADD and its post-translational modifications seem to occur in many cancers, but how it functions in cancer is complex as both overexpression and downregulation of FADD in cancers has reported BRCA to being one of the high-expressing cancer." (PMID 35227895, 2022). "However, FADD-caspase 8 signaling complex (DISC) was previously shown to be inhibited by the expression of cellular FADD-like inhibitory protein (cFLIP) in cancer cells, a protein that is sensitive to cycloheximide (CHX)." (PMID 35970851, 2022). "For instance, whether FADD possesses the same effect in mediating one anti-cancer drug in different cancer types." (PMID 36348274, 2022). "Whether FADD can participate in cancer progression through synergistic action with these signaling pathways has not been reported." (PMID 36348274, 2022). "The double-edged effect of FADD on the development of cancer drug resistance may depend on its diverse functions." (PMID 36348274, 2022). "Stimulation of cancer cell apoptosis by activating the apoptosis signaling pathway, including activation of the BH3-interacting domain death agonist (BID) and FAS-associated death domain protein (FADD)." (PMID 36209106, 2022). "The dysregulation of FADD induced by this network may contribute to the development many diseases, particularly cancer." (PMID 36348274, 2022). "Phosphorylated FADD alters the expression of cell cycle regulatory proteins (e.g., Cyclin D1 and Cyclin B1) by activating NF-κB signaling pathway, thereby mediating the G2/M transition of cancer cells." (PMID 36348274, 2022). "Therefore, the phosphorylation status of FADD is crucial for the transition of cancer cells at the G2/M boundary." (PMID 36348274, 2022).
cancer (continued). "In addition, we demonstrated that the cells resistant to anti-cancer drugs (CASP3/7/6 and FADD-deficient cells) are sensitive to treatment with TNF-α/SM, which triggers RIP1-dependent necroptosis." (PMID 33800107, 2021). "Copy number amplifications are frequently observed in the chromosomal region 11q13, which harbors besides ANO1, genes CCND1, ORAOV1, PPFIA1, FADD and CTTN, the expression of which is associated with cancer proliferation, migration, apoptosis or poorer prognosis." (PMID 33803266, 2021). "We demonstrated the resistance of FADD knocked out cells to treatment with anti-cancer drugs." (PMID 33800107, 2021). "Based on these results, we speculate that ripoptosome, a cytoplasmic complex consisting of RIP1, FADD, and caspase 8, plays a crucial role in the cell death signaling upon treatment with the anti-cancer drugs." (PMID 33800107, 2021). "However, it is still not well understood how alterations in the expression of FADD and IAPs affect death pathway signaling and contribute to resistance to therapies targeting the death pathways in cancers, especially in HNSCC differing in HPV status." (PMID 33737574, 2021). "Importantly, post-translational modifications (PTMs) and nuclear localization of FADD have been reported in cancer cells, which further challenge the pro-apoptotic competency of FADD to instigate apoptosis signaling." (PMID 32961826, 2020). "Other novel ways to directly deliver FADD protein in cancer cells are less explored." (PMID 32961826, 2020). "Therefore, investigation of FADD gene should help the understanding of cancer development, including gastric carcinogenesis." (PMID 33076854, 2020). "Given the importance of FADD in apoptosis and pro-tumorigenic NF-κB signaling, FADD protein may demonstrate a tremendous potential to mitigate cancer progression." (PMID 32961826, 2020). "It is plausible that in certain contexts or cancer cells, FADD may serve as an adaptor protein that links TNFα signaling to the pro-survival NFκB pathway." (PMID 32194778, 2020). "Importantly, cancer cells devise mechanisms to suppress FADD expression and, in turn, escape from apoptosis signaling." (PMID 32961826, 2020). "The report presented here of a pro-survival function for FADD in OS and other studies that report pro-survival functions of FADD in other cancers underscore the need to further investigate the multifunctional role of FADD in cancer initiation, progression and survival." (PMID 32194778, 2020). "Based on these observations, we proposed that sufficient availability of intracellular FADD expression could potentially target NF-κB core signaling with a concurrent reduction of anti-apoptotic expression in cancer cells." (PMID 32961826, 2020). "Formulating strategies, for direct delivery of FADD proteins into cancer cells in a controlled manner, may represent a promising therapeutic approach in cancer therapy." (PMID 32961826, 2020). "This indicates that FADD needs to interact with kinases, and kinases may collaborate with particular substrates in distinct cancer types." (PMID 31937869, 2020). "FADD downregulation in certain cancer types—such as T-LBL—might result in the reduced stability of NKAP complexes in the nucleus, contributing to NOTCH hyperactivation frequently found in T-cell lymphoblastic neoplasms." (PMID 31569512, 2019). "In addition, the levels of NFκB and TNF-R1 were higher in the mesenteric adipose tissue of cancer cachexia patients, and lower levels of FADD and NFκB in tumor tissue were also observed." (PMID 31741709, 2019). "Besides being an essential component of several death signaling pathways, FADD is also involved in numerous physio-pathological processes including cancer development, innate immunity and inflammation." (PMID 30804327, 2019). "Interestingly, we found that levels of phosphorylated FADD correlated with the proliferation capacity of tumor cells, supporting previous evidence in different cancer types." (PMID 31569512, 2019).
cancer (continued). "Moreover, as FADD can prevent necroptosis, FADD reduction in cancer would also induce a switch from apoptotic signaling to necroptosis." (PMID 31569512, 2019). "In cancer, apoptosis impairment appears as a plausible consequence of FADD reduction." (PMID 31569512, 2019). "In cancer, FADD is detected in all tumor types analyzed by RNA sequencing according to The Cancer Genome Atlas (TCGA), and FADD protein levels obtained by immunohistochemistry with two different antibodies reveal results that are consistent with RNA-seq and/or protein/gene characterization data." (PMID 31569512, 2019). "Also, a cohort study demonstrated that the release of FADD from tumor biopsies was positively correlated with cancer stage and metastasis process." (PMID 31741709, 2019). "Regulation of FADD expression by transcription factors and epigenetic mechanisms may also be altered in cancer, but limited evidence is available to confirm this." (PMID 31569512, 2019). "Finally, we gather all the available evidence regarding the clinical implications of FADD alterations in cancer, especially as it has been proposed as a potential biomarker with prognostic value." (PMID 31569512, 2019). "Expression analysis also indicated involvement of extrinsic pathway of apoptosis in PN-treated cells as increased levels of TRAIL R1/D4, TRAIL R2/D5, TNFα, Fas and FADD were observed in some of the PN-treated cancer cells at 48 h in comparison to vehicle treated cells." (PMID 29420562, 2018). "Furthermore, we found a positive correlation between BRCA1 and the three target genes in cancer cell lines and verified FADD as a novel direct target of BRCA1 by luciferase reporter, ChIP, and functional studies." (PMID 29757984, 2018). "Hence, FADD plays an important role in apoptosis in aged lymphocytes and has been reported as a co-tumor suppressor in cancer cell lines." (PMID 29757984, 2018). "Therefore, TRAIL/TRAIL-R-mediated, FADD-dependent cytokine induction represents a distinct cancer-promoting function of this ligand-receptor system." (PMID 28212753, 2017). "Not only FADD reduction may contribute to cancer, but also its phosphorylation status would determine its proliferative role." (PMID 27556297, 2016). "These and other authors suggest that assessment of FADD phosphorylation may be useful as a prognostic biomarker, and that induction of FADD phosphorylation could be a target in cancer therapy." (PMID 27556297, 2016). "They suggested that DR5/FADD/caspase-8 signaling may have an opposite function to the previous reported in regulating cancer metastasis and may depend on the tumor stage." (PMID 27764170, 2016). "Additionally, FADD has a critical role in thymopoiesis, which potentially makes T-LBL a type of cancer particularly susceptible to FADD alterations." (PMID 27556297, 2016). "However, very limited results regarding FADD phosphorylation are available in hematological human cancers." (PMID 27556297, 2016). "This is an important cytokine that plays a role in cancer, with two protein families implicated in the signaling mediated by the TNF receptor: 1) death-domain proteins, such as TRADD, FADD, TNFR1, RIP; and 2) TRAF domain-containing proteins, such as TNFR2, CD40, TRAF1, TRAF6." (PMID 26143641, 2015). "Indeed, the levels of p-FADD were high in 62% of cancers showing low levels of AK2 expression and in 75% of cancers showing DUSP26 deficiency." (PMID 24548998, 2014). "Taking the available data together, phosphorylation of FADD via JNK activation may lead not only to cell growth suppression through G2/M arrest but also directly to inhibition of cancer invasion or lymph node metastasis." (PMID 16450001, 2006). "However, the present in vitro analysis demonstrated that JNK/FADD signals affect not only in ER-positive cancer cells, MCF-7, but also in ER-negative cells, MDA-MB-231." (PMID 16450001, 2006). "In the present review, we focus on the role of the FADD adaptor in cancer." (PMID 15717929, 2005).
cancer (continued). "Moreover, treatment with carboplatin enhances FADD protein expression, thus rendering cancer cells sensitive to Fas-mediated apoptosis." (PMID 15717929, 2005). "These genes are involved in the regulation of cell cycle (CCND1, CDCA5, FOSL1, KDM2A, NUMA1, RHOD), apoptosis (FADD, ORAOV1), or the DNA damage response (DDB1, KAT/TIP60, MUS81, PACS1, RPS3), and several have been implicated in the HPV lifecycle and/or HPV-associated cancers." (PMID 40892869, 2025). "Regardless, the effect of FADD may vary between cancer therapies and require in-depth exploration." (PMID 38169587, 2024). "Therefore, the delivery of FADD proteins into cancer cells could represent a promising therapeutic approach for tumor therapy." (PMID 38891056, 2024). "Moreover, silencing FADD impaired the migration and invasion abilities of cancer cells." (PMID 38684755, 2024). "Functional enrichment suggests that the high FADD phenotype is enriched in purine pyrimidine metabolism-related pathways and cell cycle-related pathways, which are hallmarks and one of the fundamental mechanisms of cancer, suggesting that high FADD is a dysregulated, hyperproliferative LUAD subtype." (PMID 37671047, 2023). "However, the exact effects of FADD on drug resistance in cancer are still unclear." (PMID 36348274, 2022). "In summary, FADD may play the dual role of tumor suppressor or oncoprotein in cancer progression." (PMID 36348274, 2022). "Whether FADD have the same role in mediating multiple anti-cancer drugs in one cancer." (PMID 36348274, 2022). "For instance, FADD overexpression in MEFs was found to suppress LPS-induced NF-κB activation but promote LPS-induced IFNβ production, which means that FADD may possess great potential to play an anti-inflammatory role in some other cancer types." (PMID 36348274, 2022). "Therefore, a complete clarification of the ncRNA-based regulatory network of FADD may be highly beneficial to the development of effective therapeutic strategies for cancer patients." (PMID 36348274, 2022). "Therefore, the dysregulation of FADD is closely correlated with many diseases, particularly cancer." (PMID 36348274, 2022). "Whether FADD is involved in cancer drug resistance by regulating these processes." (PMID 36348274, 2022). "Nevertheless, in-depth investigations are required to elucidate the detailed mechanisms of FADD involved in inflammation regulation during cancer progression, which may provide new insights into the development of FADD-based therapeutic strategies for cancer patients." (PMID 36348274, 2022). "FADD could also mediate the effect of ncRNAs on proliferation in cancer." (PMID 36348274, 2022). "We proposed an efficient strategy to deliver FADD protein in a controlled manner with the better targeting ability of cancer cells and this therapeutic strategy may be useful to overcome temporal and uncontrolled expression modulation as observed with the conventional gene delivery approach." (PMID 32961826, 2020). "The expression of FADD in cancer cells is relatively low, and some studies have contributed that at low levels, FADD may contribute to NF-κB activation, while, seemingly in contrast to these studies, we and others reported that induced expression of FADD regulates NF-κB activation." (PMID 32961826, 2020). "However, in the majority of cancer cells, the cytosolic expression of FADD is typically suppressed." (PMID 32961826, 2020). "This may act synergistically with the FADD overexpression observed in certain cancers." (PMID 31569512, 2019). "Therefore, the decrease in FADD in tumor of CC patient could be related to FADD release, which could contribute to the inflammatory process involved on cancer cachexia development." (PMID 31741709, 2019). "However, FADD implication in cancer is complex, due to pleiotropic effects." (PMID 31569512, 2019).
cancer (continued). "Importantly, this effect was cancer cell autonomous and mediated by the membrane-proximal domain (MPD) of TRAIL-R2, independently of the DD and the apoptosis adaptor protein Fas-associated death domain (FADD)." (PMID 28212753, 2017). "Thus, we can suggest that FADD is an important functional component in apoptosis signaling and it could be a plausible novel candidate for cancer therapeutic." (PMID 26972597, 2016). "Validated miR-155 target genes are present in multiple pathways associated with cancer and cancer progression, including EMT (SMAD5), proliferation (SOCS1, INPP5D, and CSF1R), block of differentiation (SPI1, CEBPB), and apoptosis (CASP3, FADD, APAF1, and FOXO3A)." (PMID 27128908, 2016). "The diverse roles of FADD ranging from cell survival to cell death and little knowledge of regulation of FADD expression makes it an interesting subject to study and we believe that finding a miRNA targeting this gene would add a new dimension to the ongoing research in the cancer therapeutics." (PMID 19513126, 2009). "Correlation analysis demonstrated that the expression of most of the PANoptosome components was positively correlated with CNV levels in many cancers (such as BRCA, HNSC, LUSC, and OV), especially for FADD, RIPK1, and CASP6." (PMID 38436818, 2025). "An incoherent expression of FADD and RIPK2 is consistently observed across various cancer types, resulting in improper interaction and downstream signaling." (PMID 38542202, 2024). "The inhibition of c-FLIP interactions with the FADD precludes c-FLIP from its recruitment into the DISC, and allows caspase-8’s binding to the FADD, promoting TRAIL-induced apoptosis in resistant cancer cells." (PMID 38248348, 2024). "Overall, these outcomes strongly suggest that UNE-C1 triggers ICD in human cancer cells through a mechanism dependent on TLR2 activation, with the expression levels of TLR2 and FADD being critical determinants of this process." (PMID 39669578, 2024). "In contrast, while Molecules 2 and 6 showed an inhibitory role in the FADD/c-FLIP interaction in the molecular assay, they poorly restored apoptosis in resistant cancer cells overexpressing c-FLIP." (PMID 38248348, 2024). "K-means clustering of >600 000 cancer cells and cell level intensities of APAF1, procaspase-9, procaspase-3, XIAP, SMAC, BAX, BAK, BCL2, BCL-XL, MCL-1, procaspase-8, BID, FADD, FLIP, RIP3 and CIAP1 identified distinct cell cluster profiles." (PMID 39886119, 2024). "Subsequent studies have revealed a previously unappreciated role for the FADD protein as a molecular switch regulating the TNF-α- NF-κB signaling axis, thereby influencing both apoptosis and cancer cell proliferation." (PMID 38542202, 2024). "The expression levels of FASLG and FADD in almost all cancer types were higher than those in normal tissues, and FAS was downregulated in most types of cancer." (PMID 36583248, 2023). "While upregulation of FADD seems counterintuitive to apoptotic resistance, selection of this gene may instead relate to its other pleiotropic non-classical functions in inflammation, differentiation, and cell growth, with both upregulation and downregulation of FADD reported in various cancer types." (PMID 35163485, 2022). "In comparison, FADD in 12 cancer types, FASLG in 3 cancer types, RIPK1 in 19 cancer types, TLR3 in 25 cancer types, TNF in 11 cancer types, FAS in 22 cancer types, MLKL in 15 cancer types, and RIPK3 in 12 cancer types had homozygous deletions." (PMID 35748782, 2022).